RNU6-526P (RNA, U6 small nuclear 526, pseudogene)
Gene: Small nuclear RNA gene on chromosome 8 (9,371,090 to 9,371,195, reverse strand). Ensembl gene ENSG00000201815.
Homologues: Orthologues: chimpanzee U6 (100% identical), macaque U6 (88% identical), dog U6 (68% identical), rabbit U6 (65% identical), guinea pig U6 (63% identical), pig U6 (63% identical), rat LOC120099049 (58% identical), mouse Gm54928 (46% identical). Paralogues in human: RNU6-434P (76% identical), RNU6-211P (75% identical), RNU6-20P (75% identical), RNU6-1152P (74% identical), RNU6-116P (74% identical), RNU6-1316P (74% identical), RNU6-196P (74% identical), RNU6-310P (74% identical), RNU6-480P (74% identical), RNU6-1075P (73% identical), RNU6-144P (73% identical), RNU6-16P (73% identical), and 1285 more.